CDKN2A (cyclin dependent kinase inhibitor 2A)
Diseases named in the same sentence as CDKN2A in open-access papers (continued):
Sharing a sentence is not in itself a finding about the gene and the disease.
tumor (continued). "These include tumors from women that carried the minor allele of the rs11515 polymorphism in the 3′ UTR of cyclin dependent kinase inhibitor 2A (CDKN2A) that encodes both the p16INK4a and p14ARF tumor suppressors." (PMID 31572679, 2019). "The CDKN2B-CDKN2A gene cluster is commonly deleted in many types of cancer, and the tumor promoting effects of the CDKN2A-encoded p16 and p14 (ARF) tumor suppressors are well studied in melanocytic lesions." (PMID 31861163, 2019). "The induction of replicative senescence by critically short telomeres is frequently linked to the CDKN2A locus encoding the p16 and alternative open reading frame (ARF) genes, whose expression is sufficient to activate tumor suppressor networks." (PMID 30845965, 2019). "INK4a/p16 (encoded by CDKN2A) is a pan cancer tumor suppressor with a major anti-cancer role of G1 cell cycle arrest by inhibition of CDK4/6 (as part of the Cyclin D arm of the cell cycle/RB/E2F pathway)." (PMID 30890123, 2019). "In a multivariate Cox proportional hazards model adjusted for age, stage, and tumor size, CDKN2A alterations were significantly associated with a worse prognosis (HR 2.7, mOS 2.5 vs. 6.7 years, p = 0.002)." (PMID 31528332, 2019). "We found that an abnormal copy number of CDKN2A in MPM tumor cells associated with a high pulmonary asbestos fiber count (p = 0.044, Fisher’s Exact test, two-tailed)." (PMID 31138176, 2019). "Mutational profiling was carried out by targeted deep sequencing and showed that his tumor tissue harbored CDKN2A and CDKN2B loss." (PMID 31700061, 2019). "Next-generation sequencing of the tumor showed CDKN2A/B loss, MSI-stable, and low TMB, thereby ruling out the options for targeted therapies." (PMID 30739492, 2019). "Taken together, these data suggest that genetic variation within the core 9p21 CAD region relates to differential expression not only of ANRIL, but in specific cells or conditions, also of the CDKN2A/B tumor suppressors encoded in the locus." (PMID 30460243, 2018). "This region contains the CDKN2A gene, which encodes p16, a well-established tumor suppressor in a variety of tumor types, including malignant mesothelioma." (PMID 30060501, 2018). "CDKN2A alterations are present in 25% of type II pRCC tumours when loss of heterogeneity, promoter hypermethylation, and somatic mutations are considered together." (PMID 30099580, 2018). "The impact that this class of mutations can have on tumor biology is significant and is exemplified by the identification of a germline mutation in the CDKN2A tumor suppressor gene mapping 34 nucleotides upstream of the normal start site." (PMID 30425729, 2018). "The CDKN2B gene lies adjacent to the tumor suppressor gene CDKN2A in a genomic region that is frequently mutated and/or deleted in various tumor types." (PMID 29343775, 2018). "This analysis revealed that the same variables of tumor stage (HR: 1.79, 95% CI: 1.03–3.11), receipt of chemotherapy (HR: 1.64, 95% CI: 1.13–2.37), and CDKN2A copy number loss (HR: 1.51, 95% CI: 1.06–2.16) were independently associated with poor survival." (PMID 29670856, 2018). "For instance, focal or whole-arm deletion of CDKN2A gene, which encodes two important tumor proteins (p14ARF and p16INK4A), is commonly observed in leukocytes of ALL patients." (PMID 29654170, 2018). "CDKN2A is a kinase implicated in the production of p16(INK4a) and p14(ARF), well-established tumor suppressors." (PMID 30323202, 2018). "Overall, BRAF, NRAS, and CDKN2A were found mutated in 62.5%, 12.5% and 59% cell lines and in 47%, 16%, 12% tumor tissues, respectively." (PMID 29492214, 2018). "Clonality analysis revealed that CDKN2A mutations are clonal indicating a likely early event in formation of the tumours in which they were identified." (PMID 30202019, 2018).
tumor (continued). "Homozygous CDKN2A/B loss alone is insufficient for tumor formation in mice, requiring the activation of an oncogene to generate tumors in vivo." (PMID 29616301, 2018). "To more deeply investigate the role of CDKN2A expression in tumour prognosis and its association with drug target genes like FGFR3, we performed qRT-PCR expression profiling and reanalysis of existing CDKN2A and FGFR3 RNA expression data of MIBC after RC." (PMID 30258198, 2018). "The p16 protein is encoded by the CDKN2A gene that resides on chromosome 9p21 and operates as a tumor suppressing gene." (PMID 30280037, 2018). "CDKN2A encodes two proteins, p16 and p14, both of which act as tumor suppressors through regulation of the cell cycle." (PMID 30041611, 2018). "Quite identical mutation patterns between primary tumors and metastatic lesions were found for BRAF and NRAS genes; mutations of CDKN2A gene appeared to be instead selected during tumor progression." (PMID 29492214, 2018). "The disease outcome of these patients is related to the extent of tumor resection and to the co-occurrence of CDKN2A deletion together with BRAFV600E mutation." (PMID 30279357, 2018). "Consistent with human MM tumours, we identified homozygous loss of the tumour suppressor Cdkn2a in 14/15 tumours." (PMID 28577549, 2017). "Loss of CDKN2A/CDKN2B or PTPRD tumor suppressor was often used to explain the frequent chromosome 9p deletion in human cancer." (PMID 28977839, 2017). "Patients with CDKN2A hypermethylation in the tumor had a lower risk of LRR when compared to those with hypomethylated tumors, although the results were not significant (Log‐rank test P = 0.11)." (PMID 28102032, 2017). "CDKN2A promoter methylation was associated with EC tumor grade (OR = 1.79; 95% CI, 1.20–2.67) and clinical stage (OR = 2.56; 95% CI, 1.33–4.92)." (PMID 28637022, 2017). "The extremely high mutation frequency of cdkn2a/b or rb1 in tumor tissues derived by TALENs injection also supports the possibility of tumor induction by specific inactivation of cdkn2a/b or rb1." (PMID 28903419, 2017). "Expression of a tumor-suppressive network, including P16 and P19, encoding by cyclin-dependent kinase inhibitor 2A locus, facilitates suppression, while loss of CHD5 increases proliferation." (PMID 28580304, 2017). "Further investigations are, however, necessary to confirm that hypermethylation of CDKN2A exon 2 is associated with tumor proliferative activity." (PMID 28403857, 2017). "For patient 10, the CNA profile observed in the tumour (including focal loss of CDKN2A and CREBBP) was observed in all peripheral sample types taken prior to starting chemotherapy, albeit at lower levels in plasma." (PMID 28717136, 2017). "In one patient (Enza-1) with paired biopsy samples that were obtained from the same site, a P81L mutation in CDKN2A was only detected in the resistant tumor." (PMID 32913968, 2017). "In the case of cdkn2a/b, most mutations in tumor tissues of cdkn2a/b TALEN-injected F0 tp53e7/e7 zebrafish were also frame-shifts, while some were in-frame mutations." (PMID 28903419, 2017). "Given that the CDKN2A locus encodes two tumor suppressors, and that both transcripts are elevated in LXSCC tumors, we wanted to examine the presence of genetic variations across this locus." (PMID 28102032, 2017). "Only one tumor with CCNE1 amplification also had a CDKN2A locus deletion associated with weak expression of CDKN2A (0.1%), as observed in HCC1806 cells." (PMID 28566333, 2017).
tumor (continued). "The exact tumor types induced by cdkn2a/b mutations would be determined according to binding partner and/or biological context in normal and cancer cells." (PMID 28903419, 2017). "CDKN2A genes exhibited nonsense and frameshift mutations, indicating its tumor suppressor roles in OSCC." (PMID 28938622, 2017). "Sex-linked barring is a fascinating plumage pattern in chickens recently shown to be associated with two non-coding and two missense mutations affecting the ARF transcript at the CDKN2A tumor suppressor locus." (PMID 28388616, 2017). "The CDKN2A gene encodes two proteins: p16INK4a and p14ARF, which both act as tumor suppressors by regulating the cell cycle." (PMID 27880943, 2017). "For example, alterations to CDKN2A, a tumor suppressor gene that encodes a specific inhibitor of cyclin-dependent kinase (CDK) 4 and 6, are found in a wide range of human cancers." (PMID 27517925, 2016). "The LOH within the coding region of CDKN2A was associated with higher tumour grade and a higher risk of metastasis." (PMID 27682877, 2016). "Accordingly, the dysregulation of CDKN2A is associated with the development of a wide variety of tumours." (PMID 27835969, 2016). "From one such tumor (#2341), we have developed a syngeneic and orthotopic BrafV600E mutant and Cdkn2a deficient engraftment model." (PMID 27713119, 2016). "BRG1 loss is not yet recognized as a major mechanism of RB1 pathway inactivation, in part because BRG1 loss occurs concomitantly with tumor cell loss of CDKN2A (p16) or RB1." (PMID 28105458, 2016). "p16, encoded by the CDKN2A gene, is a tumor suppressor that has been widely studied in cancer research." (PMID 27199504, 2016). "Both early passage cell cultures and mouse xenograft tumors harbored the BAP1 mutations and CDKN2A deletions identical to those observed in the corresponding primary tumor." (PMID 25952750, 2015). "Of 15 cases with the heterozygous germline genotype at this SNP, six exhibited somatic deletion of one copy of CDKN2A, all of which retained the risk allele in tumour cells." (PMID 26104880, 2015). "CDKN2A deletion is one of the most frequent mutations in GBM, resulting in the loss of two tumor suppressors (p16INK4a and p14ARF)." (PMID 26439688, 2015). "Within this panel, we identified a hypermethylated region downstream of the CDKN2A gene that was associated with p16 protein expression in OPSCC and is correlated with an increase in tumor-specific expression of the CDKN2A transcript variant p14(ARF)." (PMID 25619363, 2015). "MIR31HG, which encodes microRNA-31 (miR-31), is a novel non-coding tumor suppressor positioned adjacent to CDKN2A/B at 9p21.3." (PMID 26164206, 2015). "It should also be noted that the vast majority of coding variants within the CDKN2A gene affects only one of the two tumour suppressors (either p16INK4A or p14ARF)." (PMID 26104880, 2015). "Specifically, we show that 75 % (67 tumours from 89 patients) of central high grade chondrosarcomas reveal loss or gain (polysomy) of p16/CDKN2A in at least one sample (data generated from both cohorts)." (PMID 25432631, 2015). "Although also encoded by the CDKN2A gene, p14ARF utilizes a completely different reading frame with distinct tumour suppression functions by inhibiting MDM2 and activating p5325." (PMID 26104880, 2015).
tumor (continued). "Regarding tumor suppressor genes, the deletion and the consequent loss of expression of CDKN2A/2B, located on the short arm of chromosome 9 at position 21.3, was observed in six patients in our study." (PMID 26544626, 2015). "MYH9, 10 and 14 mutant tumors also exhibited mutational inactivation and/or copy loss of commonly altered tumor suppressors CDKN2A (p16), FAT1, or NOTCH1, and infrequently altered TGFβ pathway components, TGF-B-R2 or SMAD4." (PMID 26369831, 2015). "The Cdkn2a locus encodes for two tumor suppressors: p16Ink4a and p19Arf. p19Arf is activated by c-Myc and has been demonstrated to suppress lymphomagenesis." (PMID 25691468, 2015). "NGS performed on a tumor sample from the liver biopsy obtained at the time of diagnosis revealed CDKN2A mutation A102P, ARID1A mutation I1485fs*5, CCND1 amplification, FGF19 amplification, FGF3 amplification and FGF4 amplification." (PMID 24931142, 2014). "The GEM study also reported a slightly higher prevalence of CDKN2A mutations in thinner tumours (p = 0.07)." (PMID 25780468, 2014). "ANRIL negatively regulates expression of the CDKN2A locus, which encodes three proteins known to inhibit tumor progression: p14ARF, p15INK4B, and p16INK4A." (PMID 24346158, 2014). "As a tumor suppressor gene regulating the cell cycle, cyclin-dependent kinase inhibitor 2A (CDKN2A/p16), is often found to be mutational in various types of human cancer." (PMID 24944698, 2014). "NGS of a tumor sample obtained from a liver biopsy performed at the time of diagnosis revealed CDKN2A mutation H83Y and CTNNB1 mutation T41A." (PMID 24931142, 2014). "For the UK, 3.3% of tumours with Breslow ≤1 mm had CDKN2A mutations, compared with 1.2% of those >1 mm." (PMID 25780468, 2014). "In total, we reveal that Ptprd is a tumor suppressor that can promote tumorigenesis in concert with Cdkn2a loss." (PMID 25138050, 2014). "CHD5 facilitates expression of a tumor-suppressive network that includes p16 and p19, encoded by the cyclin-dependent kinase inhibitor 2A (Cdkn2a) locus." (PMID 24454811, 2014). "KRAS mutation as well as CDKN2A methylation level was associated with prognosis and if found within the same tumor turned the prognosis was even worse." (PMID 25261372, 2014). "The p16INK4A protein product of the CDKN2A locus is known to be an important tumor-suppressor gene, which directly inhibits the kinases encoded by the oncogenes CDK4 and CDK6." (PMID 24345474, 2013). "CDKN2B is located adjacent to tumor suppressor CDKN2A in the chromosome 9, which is frequently mutated and deleted in a wide variety of neoplasms." (PMID 24098334, 2013). "In our series, CDKN2A methylation positivity correlated with more frequent right-sided disease, mucinous histology, tumor grade as well as with MSI, BRAF mutation and with KRAS mutation in the MSI setting only." (PMID 22925370, 2012). "We recently showed that most (80%) muscle-invasive tumours with FGFR3 mutations harbour homozygous CDKN2A deletions, resulting in the loss of both P16INk4A and P14ARF." (PMID 23272046, 2012). "The inhibition of the Ink4/Arf locus, which contains Cdkn2a and Cdkn2b encoding three powerful tumor suppressors, p16( Ink4a ), p19 ( Arf ), and p15 (Ink4b ), is one of the key characteristics of pluripotent stemcells." (PMID 22708059, 2012). "On the other hand, because of its effect on MDM2, the CDKN2A product, ARF, acts as a tumor suppressor; consequently its loss is associated with neoplasms." (PMID 22829758, 2012). "CDKN2A is a well-known tumor suppressor whose loss, primarily through homozygous copy number deletion, is an early driver of oncogenesis." (PMID 22962493, 2012).
tumor (continued). "The crucial role of these changes, gains in 1q, 8 and losses of 9p21.3 (including loss of CDKN2A) and 16q, has been clarified by notable tumor development and adverse clinical outcome." (PMID 22429812, 2012). "The CDKN2A gene, also known as P16, is a tumor-suppressor gene with various mutations implicated in the development of FAMMM as well as other systemic cancers." (PMID 22312493, 2011). "We focused on the exon 2 CpG island of the gene because our previous study of CDKN2A DNA methylation showed that it was more highly significantly associated with cancer compared to adjacent non-tumor lung than the promoter CpG island." (PMID 21731750, 2011). "It has also been shown that Id1 and Id3 overexpression correlates with loss of CDKN2A expression in different tumours, suggesting that in some settings Id1/3-induced cell proliferation is mediated through the inactivation of the CDKN2A-pRb pathway." (PMID 20842131, 2010). "The tumor suppressor gene CDKN2A generates at least three different transcriptional variants, each of which is thought to encode a tumor suppressor." (PMID 20565749, 2010). "This tumor-suppressive pathway is mutated in close to 100% of human cancers and specific loss-of-function mutations are found within the Rb gene or the CDKN2A gene encoding p16INK4A." (PMID 20604950, 2010). "Homozygous deletion of CDKN2A was identified in 4/9 (44%) of ESFT cell lines and 4/42 (10%) primary ESFT; loss of one copy of CDKN2A was identified in a further 2/9 (22%) cell lines and 2/42 (5%) tumours." (PMID 17533400, 2007). "In typically contaminated tumor samples, genomic DNA is composed of various ratios of WT and CDKN2A deficient DNA." (PMID 17440616, 2007). "Single copy loss of 9p21 genes was observed in 3/42 (7%) tumours, two of these single copy losses were of the CDKN2A gene (5%)." (PMID 17533400, 2007). "Lastly, the mechanisms underlying the adverse prognostic impact of STK11, KEAP1, and CDKN2A mutations, currently inferred from tumor RNA-seq data and bioinformatic analyses, remain to be experimentally validated in future in vivo and in vitro fundamental research." (PMID 41491583, 2026). "Druggability assessments identified HDAC9 as a target for approved drugs potentially repurposed for VC, while PheWAS results suggested a predicted lack of severe genetic pleiotropy for most candidates, with the notable exception of CDKN2A, which showed associations with neoplasms." (PMID 42221083, 2026). "In PTC, although our statistical results only indicate the association between CDKN2A and tumor size due to insufficient sample size, there is evidence from previous studies suggesting that CDKN2A plays a crucial role in promoting tumor cell proliferation and invasion." (PMID 39253931, 2025). "Tumor cells often show faster proliferation and differentiation than normal cells, which may be, in part, explained by CDKN2A mutations or inactivation." (PMID 41341386, 2025).